MYC (MYC proto-oncogene, bHLH transcription factor)
Diseases named in the same sentence as MYC in open-access papers (continued):
Sharing a sentence is not in itself a finding about the gene and the disease.
breast cancer (continued). "Polyamine metabolism is associated with the oncogene MYC, which drives cells to increase the expression and activity of ODC, promoting the proliferation of cancers related to dysregulated polyamine metabolism (including leukemia, lung cancer, neuroblastoma, and breast cancer)." (PMID 39275124, 2024). "In addition to mediating interactions with HER2 and the ER in breast cancer, MYC may also rewire glutamine metabolism once other oncogenic pathways are activated." (PMID 39051546, 2024). "Thus, we speculated that Narciclasine and Bruceine D could inhibit MCF7 cell proliferation through targeting MELK, CDK4, and MYC to regulate cell cycle in breast cancer." (PMID 38215156, 2024). "In contrast, in breast cancer, overexpressed SRSF1, through its function in constitutive and alternative splicing, increases BIN1 isoforms that lack pro-apoptotic functions, thereby causing BIN1 failed interaction with MYC, and leading to MYC-induced epithelial cell transformation." (PMID 38778254, 2024). "Moreover, the MYC-driven secretion of exosomes containing miR-105 in breast cancer cells triggers a MYC-gene expression program in surrounding CAFs, leading to metabolic reprogramming that enhances glucose and glutamine metabolism to fuel adjacent cancer cells." (PMID 38124183, 2023). "The oncogenic TF c-MYC plays a crucial role in fibroblast transformation into CAF-like phenotype and its transcriptional networks have been involved in the trascriptome rewiring of metastasis-associated fibroblasts, associated with disease progression in human breast cancer." (PMID 38124183, 2023). "Therefore, the expression of c-MYC can conversely modulated by VEGF in breast cancer." (PMID 36721232, 2023). "Notably, c-MYC in breast cancer cells can promote tumor progression through CAFs." (PMID 36721232, 2023). "In the GEP analysis of breast cancer, five major subtypes have been established, where over expression of c-MYC has been observed in basal-like tumors with poor prognosis compared to the other subtypes, such as luminal A, luminal B, Her-2μ positive and normal-like breast cancer." (PMID 36985413, 2023). "Thus, MYC is a clinically relevant driver of mTORi resistance that may stratify breast cancer patients for mTOR-targeted therapies." (PMID 37642941, 2023). "Indeed, constitutive expression of MYC is associated with resistance to anti-estrogen treatments, and MCF7 breast cancer cells which have acquired estrogen independence through long-term maintenance in estrogen-depleted media exhibit up-regulation of MYC and ERα." (PMID 35441158, 2022). "To investigate whether MYC directly controls immune cell tumor infiltration in vivo, we assessed the effects of MYC-activation or -inactivation in established BRCA1-deficient mouse mammary tumors in situ." (PMID 36323660, 2022). "In addition, the CSN functions in conjunction with the myelocytomatosis oncogene (MYC) to modulate the transcription of many MYC target genes, such as Ccnd2 and E2f1, which are reactivated in breast cancer metastasis to promote cell proliferation, invasion, and angiogenesis." (PMID 35883466, 2022). "Therefore, targeting the steps in ribosome biogenesis instead of c-MYC may provide new cues for reducing tamoxifen resistance in breast cancer." (PMID 35267559, 2022).
breast cancer (continued). "Interestingly, the miRNA let-7 family is responsible for the ablation of MYC in Burkitt lymphoma, thus inhibiting cancer cell progression, while it targets interleukin (IL)-6 in breast cancer, the transcription factor E2F2 in prostate cancer, and the anti-apoptotic BCL, namely, BCL-XL in the liver." (PMID 35267528, 2022). "Furthermore, ENT downregulated MYC and the G2/M checkpoint in breast cancer." (PMID 36430344, 2022). "Importantly, analysis revealed that MYC is upregulated in breast cancer stroma in correlation with disease progression, as reflected by pathological grade: expression of MYC was significantly elevated in the stroma of grade 3 tumors compared with stroma isolated from more differentiated tumors." (PMID 34169837, 2021). "Recent studies have reported that the emergence of hormone therapy resistance in ER+ breast cancers can arise through four predominant mechanisms including ESR1 mutations (18%), altered MAPK signaling (13%), MYC or transcription factor activation (9%), and other/unknown factors (60%)." (PMID 33669749, 2021). "Therefore, to identify novel compounds which act synergistically with SAHA, we performed a cell-based, high-throughput drug screen using a MYC-expressing breast cancer cell line (MDA-MB-231) with relatively high resistance to SAHA (IC50 4.6 μM) compared to neuroblastoma cell lines." (PMID 33658627, 2021). "Further mechanistic research proved that circACTN4 could competitively bind to far upstream element binding protein 1 (FUBP1) to prevent the combination between FUBP1 and FIR, thereby activating MYC transcription and facilitating tumor progression of breast cancer." (PMID 34116677, 2021). "Particularly, 22% of post-hormonal therapy HR+HER2- breast cancers displayed non-overlapping alterations in one or multiple effectors of MAPK signaling or in MYC or other transcription factors; these mutations were mutually exclusive with hotspot mutations in ESR1." (PMID 32210163, 2020). "Furthermore, 9 out of 18 sets showed a statistically significant enrichment with the p-value < 0.05, including the MYC oncogenic signature genes derived from the DNA microarray analysis of the breast cancer cells (p = 0.040, FDR = 5.6%, normalized enrichment score, NES = 1.5)." (PMID 32873298, 2020). "The lncRNA BCAR4 (breast cancer anti-estrogen resistance 4), originally identified in breast cancer, has been described to directly interact with and stabilize β-Catenin protein, which enhances the expression of Wnt target genes, such as MYC and CCND1, by preventing β-Catenin degradation." (PMID 33352769, 2020). "Therefore, blocking of the LIN28B/MYC/miR-34a-5p signaling pathway, by the LIN28B specific inhibitor, causes a dramatic inhibition of tumor growth and metastatic potential in orthotopic immunodeficient mouse models of human breast cancer cells." (PMID 32486505, 2020). "Also, the MYC/eIF4E axis is a mediator of drug resistance to BEZ-235 in breast cancer cells." (PMID 32409685, 2020). "Interestingly, MYC expression in tumor cells also promotes breast cancer progression, indicating that anti-MYC therapy could have compounding antitumor benefits, which are currently under investigation." (PMID 32685002, 2020). "Thus, MYC expression is noticeably dichotomous in primary breast cancer." (PMID 30728358, 2019). "In addition to the MYC–G9A interaction, many cross-talks between cell reprogramming factors and chromatin remodelers were identified in breast cancer; however, there might be many additional such networks that require further investigation." (PMID 31013830, 2019).
breast cancer (continued). "After MYC amplification, the next most common alterations in our analysis of the human BRCA1-deficient TNBCs were mutations and/or amplifications of PIK3CA (23/80 cases), indicating that activation of PI3K signaling is an important driver in this breast cancer subtype." (PMID 30674894, 2019). "The applied human epithelial MCF10 breast cancer progression model compares the near‐diploid non‐malignant cell line MCF10A forming polarized spheroids with the tumorigenic invasively growing line MCF10CA, which bear activating mutations of HRAS and PIK3CA, and amplified MYC." (PMID 30104419, 2018). "Upon mitogenic stimulation, MAPK signaling activates an array of downstream effectors including the transcription factor MYC, which is associated with genomic instability and progression in multiple cancers, and is known to be targeted by MEK1/2 blockade in breast cancer cells." (PMID 30108112, 2018). "Thus, MYC could be regarded as a potential biomarker and therapeutic target for breast cancer patients." (PMID 29212204, 2017). "Thus, we need new more systematic studies to acquire high quality and relatively reliable data of prognostic and clinicopathological significance of MYC to stratify breast cancer patients who would benefit from MYC targeted therapy and provide evidence to prospective treatment." (PMID 29212204, 2017). "Since increased MYC expression is oncogenic and a driver of uncontrolled cell proliferation in many cancers including breast cancer, it is conceivable that TDRD3 may regulate breast cancer cell proliferation and tumor growth at least in part through this pathway." (PMID 28698590, 2017). "Importantly, MYC-high breast cancer patients with high SAE2 levels showed poor prognosis compared to those with low SAE2, suggesting that elevated SUMO pathway function may promote the tumorigenic state." (PMID 25860128, 2015). "Importantly, c-MYC protein expression was significantly elevated in radiation-exposed breast cells, emphasising the importance of this critical transcription factor in radiogenic breast cancer." (PMID 25531321, 2015). "Thus, agents that disrupt MYC-MAX heterodimers might be useful in treating some antiestrogen resistant breast cancers." (PMID 25339305, 2014). "Several array comparative genomic hybridization (aCGH) studies of breast tumors and breast cancer cell lines point to commonly observed gains and losses on regions of chromosome 8, 13 and 17 – regions known to contain breast cancer associated genes such as BRCA2, ERBB2 and MYC." (PMID 23382830, 2013). "Amplification of MYC in 8q24.21 may contribute to the progression of breast cancer." (PMID 22920630, 2012). "Interestingly, in ER+ breast cancer these pathways were also correlated with MYC and E2F3." (PMID 21050467, 2010). "Similar to MYC gain, RB1/INTS6 loss could be evolutionarily conserved in mammary tumor development." (PMID 20735817, 2010). "The transcriptionally competent β-catenin/TCF7L2 complexes provoke an excessive expression of TCF7L2 target genes, such as the cyclin D and c-MYC oncogenes, which is a common feature in human cancers, including breast cancer (BC)." (PMID 17109766, 2006). "Notably, similar results have been described in MYC-induced breast cancer and lymphoma." (PMID 15455033, 2004).
breast cancer (continued). "Unlike colorectal cancer, where miR-32-5p directly targets PTEN/BMP5 to drive metastasis, our work reveals a breast cancer-specific mechanism: miR-32-5p suppresses FBXW7, stabilizing c-MYC." (PMID 40711670, 2025). "Critical in the upregulation of oncogenes such as MYC and BCL‐2, driving malignant transformation and cancer cell survival in numerous cancer types, including breast cancer and lymphomas." (PMID 40959208, 2025). "Gene expression correlation analysis revealed that USP30 negatively correlates with the expression of stem cell markers such as MMP2, MMP9, MYC, OCT4(POU5F1), NANOG, ALDH1A3, CD133 (PROM1), EPCAM, CD24, and ITGA6 in breast cancer cohorts." (PMID 41306556, 2025). "Elevated expression of keratin 5, keratin 17, intergrin-B4, laminin, MYC, CDK6, and CCNE1 are among the gene expression characteristics of this breast cancer subtype." (PMID 40176859, 2025). "Here, we show that treatment of breast cancer cell lines with the molecular glue, GT19630, degraded MYC, inhibited cell proliferation, blocked cell cycle progression, induced apoptosis, and decreased cell migration." (PMID 39875774, 2025). "Tamoxifen can reduce the formation of MED1 condensate in MYC oncogene, resulting in the expulsion of ER α from MED1 condensate, thus improving the drug resistance of breast cancer treatment." (PMID 40231263, 2025). "In breast cancer cells, MOF-mediated acetylation of AURKB enhances AURKB protein stability and promotes c-MYC phosphorylation, ultimately leading to c-MYC accumulation and increased tumor cell proliferation." (PMID 40710353, 2025). "Here, we showed that genetic inhibition of ITCH increased expression of GATAD2B, SOX2 and MYC, as well as mammosphere formation and CSCs population detected by ALDEFLOUR in multiple breast cancer cell lines." (PMID 40136647, 2025). "CDK1 can be considered an optimal CDK target for breast cancer treatment, promoting MYC-driven transcription and tumorigenesis through mediated ubiquitin ligase activation of FBXO28 and predicting poor survival in breast cancer." (PMID 39991589, 2025). "The aim of this study was to evaluate a novel molecular glue, dubbed GT19630, which degrades both MYC and GSPT1, for the treatment of breast cancer." (PMID 39875774, 2025). "Public data analysis from breast cancer patients revealed post-radiotherapy upregulation of the β-catenin pathway, with elevated CTNNB1, MYC, and CD44 expression, alongside reduced CDKN2A and CDH1 levels, supporting clinical relevance." (PMID 40657369, 2025). "In breast cancer cells, hsa-miR-195 induces apoptosis by targeting genes such as Bcl-2 and FASN; however, aberrant activation of MYC can antagonize the pro-apoptotic effect of miR-195 by upregulating anti-apoptotic proteins like Bcl-xL." (PMID 41210882, 2025). "The aim of this study was to investigate a novel molecular glue that degrades MYC and GSPT1 known as GT19630, as a potential new treatment for breast cancer." (PMID 39875774, 2025). "The most significantly altered segments in breast cancer included 11q13.3-Amp where mitogene CCND1 is located, and 8q24.21-Amp where oncogene MYC is located." (PMID 40740860, 2025). "In breast cancer cells, GPR89A has been identified as a novel oncogene cooperating with the MYC oncogene to promote tumour formation." (PMID 40242936, 2025). "This eventually leads to activation of cell proliferation by inducing transcription of PR targeted genes MYC and CCND1 in mouse mammary tumor models." (PMID 40176859, 2025). "A positive correlation between c-MYC and GLS expression was evidenced in both breast cancer TGCA database and in MCF-10 A cell clones overexpressing circPVT1." (PMID 40114244, 2025). "We also found novel trans-enhancer hijacking events activating known oncogenes including MYC in the small cell lung cancer cell line NCIH146, NOTCH1 in the T-cell lymphoblastic leukemia cell line CUTLL1, and CCND1 in the breast cancer cell line ZR751." (PMID 39033128, 2024).
breast cancer (continued). "Mechanistically, Notch is an inducer of MYC and NOTCH1 and MYC expression positively correlates in breast cancer biopsies." (PMID 38172915, 2024). "Previous studies have reported that FUBP1 protein can regulate c-MYC transcription by binding to the c-MYC far-upstream element (FUSE) sequence, thereby affecting tumor metastasis in lung cancer and breast cancer." (PMID 38443680, 2024). "The data show an upregulation of breast cancer related genes in T1 and C1 relative to 10A, including LRATD2, PCAT1, CASC19, CASC8, POU5F1B, PVT1 and MYC on chromosome 8." (PMID 38076897, 2024). "We timed MYC amplification in Ovarian cancers (OV; gained in 102/111 samples including gains by WGD and CN-LOH) and Breast cancers (BRCA; amplified in 156/196 samples, including gains by WGD and CN-LOH)." (PMID 38656989, 2024). "To recapitulate MYC amplification in patients, we overexpressed MYC in T24 bladder cancer cells, C4-2 prostate cancer cells and MDA-MB-231 breast cancer cells." (PMID 38424044, 2024). "One analysis of primary breast cancer samples revealed that ERBB2, FGFR1, MYC, CCND1, and PIK3CA were commonly amplified, and other well-known oncogenes such as CCND2, EGFR, FGFR2, and NOTCH3 were amplified at lower frequencies." (PMID 38611020, 2024). "Similar to the high TPX2 expressing breast cancer cells, line scan analysis of the TPX2/tubulin intensity ratio showed that high MYC Hela cells recruited increased levels of TPX2 along the length of the spindle." (PMID 38660563, 2024). "The existence of an IRES element in the 5ʹUTR region of c‐MYC mRNA has already been confirmed, and IRES‐dependent translation of c‐MYC is related to breast cancer, multiple myeloma, and other cancers." (PMID 39534558, 2024). "LINC00460 was observed to be significantly elevated in doxorubicin-resistant breast cancer cells, and LINC00460, together with FUS, promotes MYC expression by influencing the efficiency of intron removal during mRNA maturation." (PMID 39372872, 2024). "Here, we demonstrate that MYC amplification confers resistance to CDK4/6i in bladder, prostate and breast cancer cells." (PMID 38424044, 2024). "To further investigate the efficiency of A80.2HCl action on the MYC, KLHL42 and pRB1 axes identified in our study, we treated bladder cancer, prostate cancer and breast cancer cell lines with increasing doses of A80.2HCl." (PMID 38424044, 2024). "MiR-2116-5p was shown to indirectly impact the TME in breast cancer cells by being sponged by the long non-coding RNA LINC01433, activating the MYC oncogene, a potent TME regulator." (PMID 39769441, 2024). "Among the genes regulated by Bcl-2 in both melanoma and breast carcinoma models we identified CTGF, CCND3, TEAD2, FST, MYC and TP73." (PMID 38755629, 2024). "For instance, the medium of CAF induces cyclin D1, c-MYC, MMP-2 and MMP-9 expression in breast cancer cells, accelerating proliferation, migration and invasion." (PMID 36721232, 2023). "MYC, located on chromosome 8q24.21, has been identified as a frequent amplifier in HER2+ breast cancer." (PMID 37801436, 2023). "In the cross-subtype comparison of breast cancers, 82.6% of all genes across the five ALAN MYC network signatures were unique to one subtype and only 2.8% of genes (69 total including MYC) were shared by at least three subtypes." (PMID 37059746, 2023). "It is interesting to note that human chromosome 8q contains the MYC locus and chromosome 17q contains the ERBB2 locus, with amplification of these two loci highly correlated in human breast cancer." (PMID 37805590, 2023). "Of note, MYC protein levels and AZD8055 response values also significantly correlated across human breast cancer cell lines." (PMID 37642941, 2023). "When breast cancer cells and MSCs were simultaneously co-cultured, the therapeutic impact was diminished in vivo due to the upregulation of resistance-related genes (such as MUC1, MYC and BRCA1) in the breast cancer cells after cisplatin pre-treatment." (PMID 37569598, 2023).